HIF1A (hypoxia inducible factor 1 subunit alpha)
Diseases named in the same sentence as HIF1A in open-access papers (continued):
Sharing a sentence is not in itself a finding about the gene and the disease.
Insulin resistance (continued). "This enlargement can lead to local hypoxia, further exacerbating inflammation, adipocyte dysfunction, and insulin resistance by activating the oxygen-sensitive transcription factor HIF1A." (PMID 39765814, 2024). "PCBP2 overcomes palmitate-induced insulin resistance in HepG2 cells via inhibition of HIF1a and STAT378 but, in more advanced disease, PCBP2 promotes collagen production and liver fibrosis." (PMID 38291075, 2024). "HIF-1α triggering did not activate typical VEGFα-vascularization responses; rather, HIF-1α induced a collagen-driven profibrotic response that paved the path for maladaptive adipose tissue remodeling and insulin resistance." (PMID 36875140, 2023). "A number of studies have consistently demonstrated that HIF-1α expression in white adipocytes exacerbates insulin resistance and tissue inflammation." (PMID 37907745, 2023). "It is interesting to note that HIF-1α (which is stabilized through multiple mechanisms in patients with severe burns) was reported to be a mediator of insulin resistance." (PMID 35269613, 2022). "On the other hand, genetic studies by the hepatic deletion of HIF-1α alleles in mice that modeled obstructive sleep apnea revealed that HIF-1α contributes to insulin resistance and NAFLD." (PMID 35563600, 2022). "In diabetic hearts, the presence of insulin resistance attenuates the expression of HIF-1α protein, which impairs HIF-1α-mediated signaling and adaptation to hypoxia." (PMID 33604337, 2021). "Increased secretion of HIF-1α leads to the development of insulin resistance and other metabolic disorders." (PMID 33567688, 2021). "Activation of HIF-1α in adipose tissue leads to insulin resistance, while silence of HIF-1α in adipocytes protects mice from glucose tolerance by enhancing insulin secretion." (PMID 30622603, 2018). "Some reported that adipocyte-specific genetic deletion of HIF-1α protects obese mice from insulin resistance and inflammation, whereas constitutively active expression of HIF-1α results in increased insulin resistance and tissue fibrosis." (PMID 28747725, 2017). "The disruption of HIF-1α in adipocytes of a transgenic mouse model has been shown to improve the metabolic function of these adipocytes and to ameliorate insulin resistance." (PMID 28751933, 2017). "Conversely, adipocyte-specific disruption of HIF1α ameliorated HFD-induced insulin resistance in mice." (PMID 27613400, 2016). "Overexpression of HIF1α in adipose tissue has been reported to induce insulin resistance and glucose intolerance." (PMID 27613400, 2016). "In humans, HIF-1α mRNA expression correlated positively with body mass index and insulin resistance." (PMID 26619907, 2015). "In this respect, transgenic mice with constitutive activation of adipose HIF-1α developed insulin resistance and glucose intolerance." (PMID 26619907, 2015). "In contrast to adipocyte-targeted deletion of HIF-1α, loss of HIF-2α in adipocytes resulted in more pronounced HFD-induced inflammation, glucose intolerance, and insulin resistance compared to wild-type littermates." (PMID 25852648, 2015). "Others have reported a decrease in HIF-1α-dependent angiogenesis in ischemic-hindlimb models of insulin resistance and pioglitazone-treated rats." (PMID 25381014, 2015). "Exposure to exogenous hypoxia induces insulin resistance, hepatic steatosis, and dyslipidemia, in part through the activation of HIF-1α." (PMID 23049707, 2012). "By contrast, manipulation of HIF-1α in adipose tissue was shown to greatly influence peripheral insulin resistance." (PMID 23049707, 2012). "Collectively, these findings suggest that the stabilization of HIF-1α, especially during muscle contraction and hypoxia, can serve as a formidable ally in countering the onset of insulin resistance, offering a promising avenue for future exploration in metabolic health." (PMID 41155523, 2025).
Insulin resistance (continued). "MetS is characterized by caloric excess, insulin resistance, and dyslipidemia, which promote adipocyte hypertrophy, local hypoxia, and HIF-1α–driven low-grade inflammation with TNF-α, IL-6 and MCP-1 signaling, engaging NF-κB/JAK–STAT pathways and worsening insulin resistance." (PMID 41409612, 2025). "Hypertrophy of adipocytes, as well as insufficient vascularization in relation to the needs, promotes the occurrence of local hypoxia in adipose tissue, which in turn leads to an increase in the level of HIF-1α, which mediates the development of insulin resistance." (PMID 39456823, 2024). "This may closely related to hypoxia inducible factor-1α (HIF-1α) which is a vital hypoxia-induced chemokine, and it can mediate overall adipose tissue inflammation by participating in process of insulin resistance and glucose intolerance." (PMID 37635206, 2023). "However, there are also some studies reporting contradictory findings where mice expressing the dominant negative form of human HIF-1A in adipose tissues exhibit increased body weight gain, insulin resistance, and adipose tissue fibrosis." (PMID 37907745, 2023). "As increased insulin resistance could blunt the HIF-1α driven response to hypoxia, this may explain a recent finding that children from Tibet had reduced left ventricular function at pubertal age." (PMID 33604337, 2021). "Although there were no significant changes in blood glucose levels in HIF1αKOMBH mice, the serum insulin levels of HIF1αKOMBH mice were significantly increased, suggesting that mice with neuronal HIF1α knockout in the mediobasal hypothalamus developed insulin resistance." (PMID 34733235, 2021). "In muscle, the activation of Hif1a signaling causes inactivation of the TCA cycle and oxidative phosphorylation with the consequent lowering of aerobic capacity, increasing the risk for diet-induced insulin resistance." (PMID 33925229, 2021). "Oxidative stress is known to induce insulin resistance, inflammation, and activation of HIF1α." (PMID 31322414, 2019). "In the current study, we found that mice treated with BBR show a beneficial metabolically phenotype, such as a decrease in body weight gain and reduced insulin resistance, which was accompanied by decreased HIF-1α accumulation and improved adipose tissue fibrosis." (PMID 30622603, 2018). "The important role of HIF-1α in the progression of insulin resistance has been well documented." (PMID 30622603, 2018). "Interestingly, HAKO mice were refractory to HFD-induced insulin resistance, which was also found in mice with adipocyte-targeted deletion of HIF-1α generated by cross-breeding with the Kahn/aP2-cre mice." (PMID 25852648, 2015). "Therefore, the deletion of HIF-1α in adipocytes improved glucose tolerance via two distinct pathways: decrease of insulin resistance and improvement of insulin secretion." (PMID 24705496, 2014). "We propose that HIF-1α ASO treatment improved hepatic insulin resistance via two major mechanisms." (PMID 23049707, 2012). "A recent study shows that the use of pioglitazone in pubertal hypoxic rats could attenuate insulin resistance and restore the protective cardiac Hif-1α signaling in the hypoxic myocardium, which maintains the adaptive cardiac metabolism and preserves cardiac function." (PMID 33604337, 2021). "However, when they enter puberty, the rise of insulin resistance attenuates myocardial expression of Hif-1α and reduces the capacity of the heart to use glucose, which disrupts the adaptive cardiac metabolic program, decreases ATP production and leads to cardiac dysfunction." (PMID 33604337, 2021). "Also oxidative stress through TCF7L2/NF-kB/MAPK/HIF1A/SREBP regulatory cascade via insulin, MAPK and Calcium signaling pathways, may activate inflammatory responses than in turn causes insulin resistance." (PMID 20942928, 2010).
Insulin resistance (continued). "Inhibition of LOX activity in transgenic HIF-1α mice resulted in an improvement in the insulin sensitivity which highlights the critical role of LOX in HIF-1α mediated fibrosis and insulin resistance." (PMID 30622603, 2018). "The aggravated insulin resistance reported in HIF-2α knockdown mice may be due to unchecked HIF-1α-driven adipose dysfunction, as myeloid cell-specific deletion of HIF-1α protects against high-fat diet-induced adipose tissue dysfunction." (PMID 37124241, 2023). "In cell models, CYP17A1 was found to be involved in glucose metabolism by increasing glucose intake and utilization, through activating IGF1/mTOR/HIF1-α signaling way, which was consistent in CYP17A1 knockout mice with impaired glucose tolerance and insulin resistance." (PMID 37370070, 2023). "The present data proved that GHR not only promoted the secretion of RBP4 from the liver by activating STAT5 but also maintained circulating RBP4 homeostasis and repressed renal clearance of RBP4 by provoking activation of the HIF1α/TTR axis, thus inducing systemic insulin resistance." (PMID 34373742, 2021). "Previous studies found that activation of HIF-1α will initiate WAT fibrosis and insulin resistance." (PMID 30622603, 2018). "As a recent study has demonstrated the uncoupling of adiposity and insulin resistance, HIF-1α probably has no direct effect on adiposity." (PMID 24705496, 2014). "In mouse adipose tissue, saturated fatty acids can trigger HIF‐1α expression via increasing adipocyte oxygen consumption through binding to ADP/ATP translocase 2 (ANT2) to enhance uncoupled respiration in mitochondria, which will result in adipose fibrosis, inflammation and insulin resistance." (PMID 40045164, 2025). "Similarly, another study showed that depletion of HIF-1α mRNA with antisense oligonucleotides (ASO) may improve hepatic steatosis, liver insulin resistance, dyslipidemia, and induces glycogen accumulation in the liver." (PMID 24564828, 2014). "In an insulin resistance model, we previously demonstrated that VAT expansion was accompanied by a reduced vascular density and decreased HIF-1α mRNA levels, whereas treatment with LGT improved vascularization without affecting HIF-1α expression." (PMID 41007316, 2025).
lung adenocarcinoma (85 papers, 2006 to 2025). A carcinoma that arises from the lung and is characterized by the presence of malignant glandular epithelial cells. "Collectively, the correlation analysis indicates that HectH9 expression correlates with HIF-1α levels and their association indeed occurs in lung adenocarcinoma samples." (PMID 27934968, 2016). "Interestingly, HIF-1α stabilization in human lung adenocarcinoma epithelial cells infected with IAV seems to be caused by inhibition of the proteasome and decreases in the expression of the factor inhibiting HIF-1 (FIH-1)." (PMID 33135539, 2020). "HIF-1α promotes VM formation in various tumors, including lung adenocarcinoma, cervical cancer, and liver cancer, by regulating the expression of VM-related molecules." (PMID 40140670, 2025). "It has previously been reported that IL‐11 promotes tumour progression and EMT in lung adenocarcinoma through the activation of the STAT3/HIF‐1α/EMT signalling pathways." (PMID 40673604, 2025). "Our study has revealed the role of HIF‐1A on CCL2 expression when examining the HIF‐1A silenced or overexpressed lung adenocarcinoma cell lines." (PMID 35658112, 2024). "Hypoxia‐associated stabilization of HIF‐1A markedly enhanced miR‐210‐3p expression, which directly targets CCL2 downregulation in lung adenocarcinoma, resulting in impaired monocyte infiltration and the stimulation of macrophage TAM polarization." (PMID 35658112, 2024). "Knockdown of HIF-1α blocked hypoxia-induced recruitment of CD4+CD25+ Treg cells in lung adenocarcinoma cell lines." (PMID 39232704, 2024). "In other tumor types some interesting findings have been published, where HIF-1α interacted with the NRP1 promoter in lung adenocarcinoma and induced cell metastasis and vasculogenic mimicry." (PMID 36376373, 2023). "The concurrent inhibition of IL-1β/miR-144-3p/WT1D by a miR-144-3p mimic and IL-1β/NF-κB/COX-2/HIF-1α by celecoxib suppresses lung adenocarcinoma cell growth with a synergistic effect." (PMID 37460927, 2023). "Interleukin-1β (IL-1β) plays a vital role in the transformation between inflammation and cancer in lung adenocarcinoma via the IL-1β/NF-κB/COX-2/HIF-1α axis." (PMID 37460927, 2023). "This tyrosine-phosphorylated β-catenin gets complexed with SRC and HIF1α in primary human lung adenocarcinomas and lung tumor cell lines to promote the transcriptional activity of HIF1α and hypoxia-induced EMT." (PMID 35359365, 2022). "The results showed that there was a significantly higher interaction of YAP1 and HIF1α in lung adenocarcinomas as well as lung squamous cell carcinomas compared with normal tissues." (PMID 35937460, 2022). "The Kaplan-Meier overall survival curves for the expression of HIF-1α/α-SMA% in lung adenocarcinoma patients showed that the expression of HIF-1α in fibroblasts was negatively correlated with the overall survival time." (PMID 36439884, 2022). "In the lung adenocarcinoma cell line A549, hypusinated eIF5A was shown to be important for hypoxia-inducible factor 1-alpha (HIF-1A) protein induction under hypoxia." (PMID 36511302, 2022). "Consistent with inhibition of MYC and HIF1α, administration of echinomycin inhibited growth of lung adenocarcinoma xenograft and a syngeneic lymphoma model in mice." (PMID 33572152, 2021). "Our IHC results showed the sporadic staining of HIF-1α (+) but prevalent TMEM45A staining (+++) in all 17 human lung adenocarcinoma tissues." (PMID 35008313, 2021). "Herein, our study explored the role of the HIF-1α/NRP1 axis in mediating lung adenocarcinoma metastasis and VM formation." (PMID 33850110, 2021). "HIF-1α plays an important role in inducing lung adenocarcinoma cell metastasis and VM formation via upregulation of NRP1." (PMID 33850110, 2021). "In the present study, the expression of DEC1 and HIF-1α was induced by both copper and hypoxia, which is consistent with an earlier study showing that DEC1 and HIF-1α are tumor hypoxia markers during the process of lung adenocarcinoma progression." (PMID 31652494, 2019).
lung adenocarcinoma (continued). "We found that HIF-1α activity is significantly activated in lung adenocarcinoma patients with an AK4 metabolic gene signature." (PMID 30696468, 2019). "It has been shown that treatment with a small molecule inhibitor of HIF-1α, PX-478, inhibited progression and spread of orthotopic human small cell lung cancer and lung adenocarcinoma in mice." (PMID 30250643, 2018). "Some transcription factors including Slug, Zeb-1, Twist, Snail, and HIF1α, were predicted to be associated with EMT in lung adenocarcinoma based on both immunohistochemistry and in vitro experiments." (PMID 29568357, 2018). "We found that the deficiency of compensatory PIMT expression under increased ER stress induces EMT and cancer invasion in lung adenocarcinoma via a HIF1α signal." (PMID 29568357, 2018). "Accordingly, a retrospective study suggested that application of NTG plus docetaxel and carboplatin in patients with operable lung adenocarcinoma increases the response with decreased expression of HIF-1α and VEGF, supporting an antiangiogenic activity." (PMID 29568362, 2018). "We found that GBE1 and HK2 expression pattern has a highly positive correlation with HIF1α in lung adenocarcinoma and squamous carcinoma patients." (PMID 28423489, 2017). "We generated lung adenocarcinoma stem-like cells from spheroid culture and induced their transdifferentiation by a two-stage method of knocking down HIF1α expression followed by vitamin Dand suberoylanilide hydroxamic acid (VD3/SAHA) treatment." (PMID 27588392, 2016). "First, we stably knocked down HIF1α expression in SPC-A1 lung adenocarcinoma cells by HIF-1α shRNA lentiviral particles, which resulted in changing the stem-like cells to an intermediate differentiated state (named HIF1α-KD)." (PMID 27588392, 2016). "We stably depleted HIF1α expression in SPC-A1 lung adenocarcinoma cells by HIF-1α shRNA lentiviral particles." (PMID 27588392, 2016). "In lung adenocarcinoma, expression of HIF1α was significantly higher in cases with vascular invasion, lymph node involvement, and vascular endothelial growth factor-A expression." (PMID 24567056, 2014). "On the other hand, DHA enhanced the toxicity of cisplatinum in lung adenocarcinoma cells in vivo and this effect was accompanied by reduced expression of HIF-1α and VEGF and reduced tumor microvessel density." (PMID 24904829, 2014). "The incidence of lung adenocarcinoma increases rapidly, and hypoxiainducible factor-1α (HIF-1α), cyclooxygenase-2 (COX-2), E-cadherin play an important role in the proliferation and differentiation of cancer cell." (PMID 21426663, 2011). "A possible explanation for this is the reciprocal regulation between PER1 and HIF1α, a potential role for HIF3α, or that hypoxia has context specific roles in molecular subsets of lung adenocarcinoma." (PMID 40715535, 2025). "To elucidate whether HIF1α participates in regulating the malignant features of lung adenocarcinoma mediated by ERCC6L, we silenced HIF1α in ERCC6L-overexpressing A549 cells." (PMID 40691138, 2025). "Notably, elevated levels of HIF-1α, VEGF, and CCL28 are linked to a greater infiltration of Treg cells in lung adenocarcinoma samples, and high levels of HIF-1α and HIF-2α are associated with poor prognoses in both SCLC and NSCLC." (PMID 38539448, 2024). "Of all 4 NETs-related lncRNAs that are involved in the prognostic signature, it has been proved that lncRNA-FAM83A-AS1 could promote tumor progression in lung adenocarcinoma, via promoting the HIF-1α/glycolysis axis." (PMID 36419832, 2022). "However, based on our molecular mechanism that explains K-Ras targeting, we included in our cellular analysis KRAS mutant, HIF-1α high, and/or Gal3 high cancer types, such as pancreatic and lung adenocarcinoma." (PMID 33672199, 2021).